FTO (FTO alpha-ketoglutarate dependent dioxygenase)
Diseases named in the same sentence as FTO in open-access papers (continued):
Sharing a sentence is not in itself a finding about the gene and the disease.
cancer (continued). "FTO is an oncogene of LUSC, and its increased expression can promote the growth of cancer cells." (PMID 36553648, 2022). "Demethylase FTO played an oncogenic role in BC, AML, and other malignant tumors." (PMID 36517820, 2022). "On the other hand, FTO and ALKBH5 are prevalently deleted in human cancers." (PMID 32111216, 2020). "In other cancer types, the role of ALKBH5 in resistance to radiotherapy has never been reported and only one study on cervical cancer has reported the role of the mRNA demethylase FTO on radioresistance." (PMID 33375621, 2020). "RNA methyltransferases (such as METTL14, METTL3 and TAP), the demethylases(such as ALKBH5 and FTO), and the binding proteins (such as YTHDF2 and YTHDF1) are often upregulated in a variety of human cancer types to increase the expression of oncogenes and oncoproteins." (PMID 33136551, 2020). "Meclofenamic acid is such a potential drug example as it is a very selective inhibitor for a certain eraser (FTO), but, although promising, such drugs are not specific for multiple cancers, because of cancer heterogeneity." (PMID 30654440, 2019). "Indeed, increasing m6A through knocking down adenosine demethylases (FTO and ALKBH5) or overexpressing adenosine methyltransferases (METTL3 and METTL14) suppressed the cancer cell proliferation." (PMID 29228737, 2017). "Metformin ́s anti-cancer effects may be traced back to its capability to methylate DNA, which may attenuate FTO-PRL-PIP well as FTO-mTORC1 signaling." (PMID 26691922, 2015). "Multiple cancer studies show that METTL3-installed m6A marks on SLC7A11 can be read by IGF2BP proteins to stabilize the cystine transporter transcript, elevate glutathione synthesis, and suppress ferroptosis, and FTO likewise protects colorectal tumors by sustaining SLC7A11/GPX4 expression." (PMID 41280938, 2025). "While their cancer inhibitory effects have not yet been fully validated through preclinical studies, these discoveries provide valuable insights into the structure and properties of FTO inhibitors." (PMID 40823087, 2025). "In addition to FTO inhibitors, the inhibitor of METTL3, STM2457, as a highly efficient and selective inhibitor, with in vivo activity and therapeutic efficacy, marks the first evidence of the effectiveness of RNA methyltransferase inhibitors in cancer therapy." (PMID 39473440, 2024). "Of 94 germline familial variants identified with predicted functional impact, 37 SNPs/indels were detected in 28 genes, 2 of which (MLH1 and PRH1-TAS2R14) have known association with CRC and 4 others (PPP1R13B, LAMA5, FTO, and NLRP14) have known association with non-CRC cancers." (PMID 37627102, 2023). "Our results revealed that in GBM cancer cells, expression of CD274 (PD-L1), PDCD1LG2 (PD-L2), LGALS9 (Galectin-9), and PVR (CD155) were positively correlated with the expression of multiple m6A regulators, especially YTHDF2, YTHDF3, LRPPRC, METTL3, RBM15B, FTO, and ALKBH5." (PMID 35558067, 2022). "FTO and ALKBH5 were the main m6A demethylases, which could reverse RNA methylation by oxidizing the N-methyl group at m6A site to a hydroxymethyl group, and were involved in the development of immune diseases and cancer." (PMID 36619747, 2022). "In addition to the contradictory phenomena about the function of FTO in different cancers, the role of FTO in PTC has not been fully elucidated." (PMID 35090515, 2022). "Noticeably, inhibitors of FTO and ALKBH5 are effective in certain subtypes of AMLs and some solid tumors where FTO or ALKBH5 is overexpressed and promotes tumorigenesis, suggesting that these inhibitors may have promising and broad roles in cancer therapy." (PMID 34381710, 2021). "Besides FTO, other m6A regulators were also intimately interconnected with hub genes in the conserved subnetwork and EMT signature genes, highlighting their intensive functional crosstalk in mediating cancer metastasis." (PMID 31069256, 2019).
cancer (continued). "Therefore, interaction between FTO and STAT3 may suggest potential implication of FTO in cancer development, as it has already been suggested." (PMID 24410832, 2014). "The role of m6A and FTO in drug resistance is not well established, but some evidence indicates that they may regulate the expression and stability of genes that affect the chemosensitivity of cancer cells." (PMID 37605223, 2023). "Moreover, CS1 and CS2, two potent small molecule inhibitors of FTO, exert effective anti-tumor effects by suppressing immune checkpoint gene expression, especially LILRB4, in an m6A-dependent manner, thus sensitizing cancer cells to T cell cytotoxicity in leukemia and PC models." (PMID 37015927, 2023). "Therefore, speculating that inhibitors of METTL3, IGF2BP, FTO, and ALKBH may be promising targets for cancer therapy is reasonable, and moreover, combination of these inhibitors with PD-1 inhibitors may enhance the efficacy of anti-PD-1 therapy to overcome drug resistance." (PMID 37485079, 2023). "Studies have shown that FTO is an important component of m6A modification, which not only plays a key role in obesity-related diseases but also participates in the occurrence, development, and prognosis of many cancers, regulates cancer stem cell function, self-renewal and metastasis." (PMID 35711459, 2022). "Surprisingly, we find that several commonly studied RNA modification enzymes such as METTL3 or FTO are not significantly upregulated in most cancer types, whereas several less-characterized RMPs, such as LAGE3 and HENMT1, are dysregulated in many cancers." (PMID 32375858, 2020). "Surprisingly, we found that FTO expression levels are not significantly correlated with patient survival in LAML, despite this cancer type being used to test FTO inhibitors." (PMID 32375858, 2020). "Although the FTO inhibitor, entacapone, has been approved by The Food and Drug Administration (FDA) for the treatment of cancer and other related diseases, specific inhibitors have not yet been identified for other m6A regulatory proteins." (PMID 32911345, 2020).
metabolic disorders (58 papers, 2008 to 2026). "Conversely, reduced FTO activity has been linked to metabolic disorders and neurodevelopmental abnormalities." (PMID 40870000, 2025). "The FTO gene has also been associated with type 2 diabetes, growth retardation, developmental delay, metabolic disorders and hypertension." (PMID 41007963, 2025). "The relationship between different genetic variants and BMI in KOA patients has been shown, among which there are a large number of genes associated with metabolic disorders (FTO, ADIPOQ, LEP, SREBP2) and other genes (GDF5, TGFB1, etc.)." (PMID 38424630, 2024). "The analysis of rare and low-frequency variants in the FTO gene will expand information about the role of these variants in metabolic diseases." (PMID 37888112, 2023). "In this study, we performed an association analysis of NAFLD with nine FTO gene polymorphisms that have been previously found to be associated with metabolic disorders." (PMID 33817272, 2020). "No direct relationships were demonstrated between MetS and the gene polymorphisms analyzed in our study except for the FTO rs9939609, whose A allele and A/A genotype seemed to predispose to metabolic disorders." (PMID 30271660, 2018). "The only exception was the FTO rs9939609, whose A allele and A/A genotype seemed to predispose to metabolic disorders." (PMID 30271660, 2018). "The FTO variants rs9939609 and rs17817449 have been related to metabolic disease." (PMID 40864759, 2025). "Determination of the FTO genotype may help to identify patients at increased risk of developing metabolic disorders and hence pre-eclampsia." (PMID 41234028, 2025). "The relationships of FTO gene polymorphisms with metabolic diseases have been extensively studied." (PMID 33817272, 2020). "Furthermore, the expression levels of m6A modification‐associated proteins, such as METTL3 and FTO, in the blood may also be indicative of metabolic disease onset, thereby providing auxiliary diagnostic value." (PMID 40066222, 2025). "Hence, we investigated the association of two previously studied FTO polymorphisms with vitamin B12 concentrations and metabolic disease-related outcomes and examined whether these associations were modified by dietary factors and physical activity." (PMID 31516636, 2019). "Despite its relevance, investigations examining the impact of maternal metabolic disorders such as GDM on FTO-dependent m6A demethylation and its consequent influence on cardiac development remain scarce." (PMID 41509912, 2026). "As a predictor of metabolic disorders, the FTO gene plays a conclusive role in the control of energy balance and is highly expressed in many tissues, including fat and liver." (PMID 40864759, 2025). "The results from this study can provide an opportunity to unveil the interrelationships among variants in FTO and PPARD, metabolic disorders and CAD." (PMID 38161971, 2023). "As a predictor of metabolic disorders, the FTO gene plays a conclusive role in the command of energy balance and is highly expressed in many tissues, including fat and liver." (PMID 33817272, 2020). "A series of methylases are involved in the development of metabolic diseases; among them, FTO was found to play a pivotal role in promoting disease, YTHDC2 was believed to suppress disease development, while the role of METTL3 and METTL14 in metabolic disease still needs to be further investigated." (PMID 40066222, 2025). "Finally, the potential of FTO inhibitors as therapeutic agents for age-related cognitive decline and metabolic disorders is a tantalising prospect that should be explored further." (PMID 39984825, 2025). "The identification of atropine as a novel FTO inhibitor opens new research avenues, emphasizing the need for further experimental validation to evaluate its therapeutic potential in weight management and metabolic disorders." (PMID 39494311, 2024).
metabolic disorders (continued). "A proper understanding of FTO function in human diseases could lead to new treatment approaches, potentially unlocking novel avenues for addressing both metabolic disorders and malignancies." (PMID 39744011, 2024). "Given the possible role of adiponectin as a promising therapeutic target against highly prevalent metabolic diseases such as T2D, future studies aiming to unravel mechanisms related to FTO rs9939609 regulating plasma adiponectin concentrations different from body adiposity are warranted." (PMID 36979984, 2023). "FTO gene is considered to play an important role in many metabolic diseases." (PMID 34801066, 2021). "FTO is involved in the development of many metabolic diseases." (PMID 34881240, 2021). "FTO polymorphisms are associated with type 2 diabetes which is a metabolic disorder in the context of insulin resistance and relative lack of insulin due to dysfunction of pancreas islet cells." (PMID 26018652, 2015). "The lower predispositions to weight gain and metabolic disorders corresponded well with the FTO risk allele non-carriers compared to the carriers." (PMID 25888059, 2015). "Thus, FTO plays an important role in the development of metabolic disorders and is an interesting target for therapeutic agents." (PMID 25144618, 2014). "The first potential mechanism by which FTO polymorphisms affect MetS susceptibility could be that FTO variants cause aberrant expression of the FTO gene, which in turn disturbs the methylation status of FTO-targeted mRNAs and other non-coding RNAs, resulting in metabolic disorders as well as MetS." (PMID 37375547, 2023). "Finally, since FTO negatively regulates m6A levels and positively regulates adipogenesis, FTO inhibitors may provide a novel therapeutic strategy for metabolic diseases." (PMID 33922187, 2021). "Therefore, a better understanding of these pathways may lead to therapeutic approaches to treat these metabolic diseases by targeting hepatic FTO." (PMID 30388740, 2018). "To summarize, the findings of the present study demonstrated that dysregulation of the FTO/m6A/ATG16L1 axis impairs autophagy in meniscus cells, thereby promoting bioenergetic metabolic disorders and accelerating meniscus degeneration and OA." (PMID 39804978, 2025). "Pyrosequencing analyses were performed for the candidate genes KCNJ11, PPARγ, PDK4, KCNQ1, SCD1, PDX1, FTO and PEG3 in peripheral blood leukocytes (PBLs) from 25 patients diagnosed with only T2D, 9 patients diagnosed with T2D and MetS and 11 control subjects without any metabolic disorders." (PMID 28727822, 2017).
cardiovascular disease (44 papers, 2013 to 2025). "The data about the association of the FTO gene with cardiovascular disease in Asia is sparse and limited." (PMID 39257882, 2024). "Increasing evidence suggests a correlation between genetic variations in the FTO gene and cardiovascular disease (CVD) risk." (PMID 39192357, 2024). "Here, we review the association between FTO genetic variants and cardiovascular disease risk, summarize the role of FTO as an m6A demethylase in cardiovascular disorders, and discuss future research directions and possible clinical implications." (PMID 37238719, 2023). "Several studies have been conducted to further investigate how the FTO rs9939609 variant affects cardiovascular disease through interaction with factors such as race and lifestyle." (PMID 34221238, 2021). "Evidence on the relationship between FTO and cardiovascular disease (CVD) exists from studies showing the association of FTO gene variants with CVD risk, independently of BMI." (PMID 31064394, 2019). "The FTO gene has recently become one of the most extensively investigated genes associated with body mass and has been shown to play a role in cardiovascular diseases as well." (PMID 26878843, 2016). "In Caucasian US women, an interaction between the risk allele of the FTO rs8050136 polymorphism mediated by BMI and low physical activity yielded increased cardiovascular disease risk." (PMID 27680100, 2016). "First data on this have been inconsistent: showing either a BMI-independent or a BMI-dependent association of FTO with cardiovascular diseases." (PMID 26431034, 2015). "The causal effects of adiposity across multiple metabolic measures corroborate prior Mendelian randomization studies, which have examined the role of the FTO locus on standard metabolic risk factors and cardiovascular disease." (PMID 25490400, 2014). "FTO gene variants also correlate with higher risks of T2D and cardiovascular diseases." (PMID 39125390, 2024). "Furthermore, it is very important to reveal the exact role of FTO polymorphisms in cardiovascular disease via in vivo knock-in of mutant FTO in order to provide biological support to the genomic association studies." (PMID 34221238, 2021). "For this very reason the question arose whether FTO genotype might bear a direct risk for cardiovascular diseases." (PMID 26431034, 2015). "FTO is directly involved in the physiological processes of hypertension, ischemic cardiomyopathy, and heart failure, and it could be a pathogenic factor and potential therapeutic target for various cardiovascular diseases." (PMID 39157458, 2024). "However, the data on an association of FTO with cardiovascular diseases remains conflicting." (PMID 26431034, 2015). "Another investigation revealed that FTO can modulate the m6A demethylation pathway to target mRNAs, influencing the onset and progression of cardiovascular diseases across different ethnic groups." (PMID 39994404, 2025). "The dynamic changes in the expression and activity levels of METTL3 and METTL14, as well as the m6A demethylase FTO, can serve as potential biomarkers for cardiovascular diseases." (PMID 40005339, 2025). "Previous research has indicated that both METTL14 and FTO are significant in the context of cardiovascular diseases." (PMID 40606020, 2025). "FTO, an m6A demethylase, was identified as the key m6A regulator in cardiovascular disease, notably in cardiac remodelling post MI." (PMID 35892568, 2022). "Lead SNPs nearby GCKR, FTO, ZPR1, and APOE were associated with various traits including cardiovascular diseases and/or PhenoAge biomarkers." (PMID 34038024, 2021). "FTO rs9939609 genotype frequencies of males and females were analyzed separately due to known gender differences for developing cardiovascular diseases, especially for AVS." (PMID 26431034, 2015). "Further studies on the relationship between FTO and various cardiovascular diseases may provide a novel therapeutic approach to prevent and treat various cardiovascular diseases." (PMID 39157458, 2024).
cardiovascular disease (continued). "So there is a need to investigate the effect of the FTO gene variant association on cardiovascular disease on the basis of conventional and nonconventional risk factors." (PMID 39257882, 2024). "Together with previous findings, this study might add a conceptual framework for targeting FTO as a therapeutic for various cardiovascular diseases." (PMID 35402566, 2022). "Based on the findings of this study, carriers of A-allele of FTO rs9939609 polymorphism had lower levels of HDL-c and might be more susceptible to metabolic and cardiovascular diseases." (PMID 34801066, 2021). "The prevalence of risk factors of cardiovascular disease after anticancer therapy is not FTO gene polymorphism-dependent." (PMID 29675043, 2018). "Virtually nothing is known concerning the role of FTO in cardiovascular disease." (PMID 24019958, 2013). "Additionally, the FTO gene also played a potential role in cardiovascular diseases (CVD)." (PMID 36376549, 2022). "Currently, research on m6A methylation detection in cardiovascular diseases primarily focuses on the expression of METTL3 and FTO." (PMID 40005339, 2025). "Since that time, m6A methylation has been extensively studied, and its functions, mechanisms, and effectors (e.g., METTL3, FTO, METTL14, WTAP, ALKBH5, and YTHDFs) in various diseases, including cardiovascular diseases, have rapidly been investigated." (PMID 34221238, 2021). "In recent years, many studies have revealed the critical roles of m6A methylation in cardiovascular diseases, which were exemplified by abnormal levels of m6A modification as a result of methyltransferases (writer, Mettl3, and Mettl14) and demethylases (eraser, ALKBH5, and FTO)." (PMID 35004673, 2021).